EGFR (epidermal growth factor receptor)
Diseases named in the same sentence as EGFR in open-access papers (continued):
Sharing a sentence is not in itself a finding about the gene and the disease.
lung cancer (continued). "Notably, mutations of the EGFR, epidermal growth factor receptor, are known to be related to lung cancer, interfering with the signaling pathways within the cell triggered to promote cell growth and division (proliferation) and cell survival." (PMID 27417985, 2016). "The anti-proliferative activity mechanism of 5i on EGFR wild type lung cancer cells and EGFR double mutation lung cancer cells might be different." (PMID 27786281, 2016). "Therefore, we conducted this meta-analysis to investigate the diagnostic accuracy of cfDNA for detection of the two main EGFR mutations in tumor tissues in lung cancer." (PMID 27081078, 2016). "Our findings suggest that the EGFR inhibitors can facilitate anti-tumor adaptive immune responses by breaking tolerance especially in EGFR driven lung cancer that are associated with overexpression of PD-L1 and genes related to antigen presentation and inflammation." (PMID 27467256, 2016). "However, the association of the EGFR gene copy number and the content of mutant EGFR DNA in EGFR mutation lung cancer tissues still need further study." (PMID 27368002, 2016). "Cell-free DNA from six of the lung cancer patients contained the EGFR T790M mutation." (PMID 27428049, 2016). "Moreover, the EGFR mutation rate of younger lung cancer patients was significantly lower than that in the older group." (PMID 27191886, 2016). "Thus, XRCC3, XRCC5, DNA adduct levels, and HPV 16 E6 oncoprotein levels were contributors to EGFR gene mutation in lung cancer patients." (PMID 26918347, 2016). "It is largely unknown why certain demographic populations are at elevated risk for development of EGFR mutant lung cancer, but prior pulmonary tuberculosis may be a contributing factor." (PMID 26654942, 2016). "The present study also revealed that EGFR mutations in advanced lung carcinoma were more frequently associated with intra-thoracic metastases to the lung and pleura, and the absence of lymphadenopathy and extranodal invasion, compared to the KRAS and ALK mutations." (PMID 27518729, 2016). "Over the last decade, the development of targeted therapy has prompted efforts to genetically classify patients with lung carcinomas into subsets, such as epidermal growth factor receptor (EGFR)-mutated type, and anaplastic lymphoma receptor tyrosine kinase (ALK)-rearranged type." (PMID 27648828, 2016). "In line with the regulatory role of miRNAs in the EGFR signaling pathway, the aberrant expression and/or mutation(s) of EGFR may also alter the expression of miRNAs in lung cancer." (PMID 26273639, 2015). "Given the simplicity of the methodology, this system may help to usher in a new phase in EGFR mutation testing for the diagnosis and treatment of lung cancer patients." (PMID 25591975, 2015). "The EGFR mutation testing is another method that has been developed for lung cancer genetic test." (PMID 25802891, 2015). "To solve this problem and provide a model, which clinicians or physician scientists could refer to, we examined and compared the potency of EGFR-TKIs against lung cancer cell lines harboring various types of EGFR mutations." (PMID 26515464, 2015). "Interestingly, miR-128 loss of heterezygosity was frequently detected in lung cancer samples, in correlation with patient survival following treatment with an EGFR-specific TKI." (PMID 26287249, 2015). "The present study reports a case of primary lung cancer that metastasized to the stomach and to the best of our knowledge, is the first to identify discordance in epidermal growth factor receptor (EGFR) mutation status between the primary tumor and gastric metastasis." (PMID 25663915, 2015).
lung cancer (continued). "Lung cancers often harbour a mutation in the epidermal growth factor receptor (EGFR) gene." (PMID 26400668, 2015). "The KRAS gene also mutated exclusively with EGFR in lung cancers." (PMID 26212640, 2015). "Furthermore, we provide evidence of the key role of NF-κB signaling in driving lung cancer resistance when effective and persistent inhibition of EGFR is achieved in the presence of the T790M mutation." (PMID 26015408, 2015). "However, irreversible EGFR inhibitors have been shown to have a more robust in vitro effect on exon 20 mutated lung cancer and clinical trials exploring their therapeutic potential are ongoing." (PMID 26697520, 2015). "In addition, EGFR mutation analysis performed on lung cancer CTCs was reported to be more sensitive than conventional serum nucleic acid analysis." (PMID 26267323, 2015). "The success of EGFR and ALK inhibitor therapies in lung cancer patients with EGFR mutations and EML4-ALK translocations initiated the era of targeted therapy in advanced NSCLC and shifted treatment from platinum-based chemotherapy to molecularly targeted therapy." (PMID 25789627, 2015). "We also successfully detected EGFR mutations in the lavage obtained from a lung cancer patient." (PMID 25591975, 2015). "Interestingly, HER2 was recently reported to be overexpressed in lung cancers with acquired resistance to EGFR targeted therapy that lack the secondary T790M mutation." (PMID 26375550, 2015). "A study by researchers at the Ohio State University Comprehensive Cancer Center demonstrated that treatment of EGFR-mutated lung cancer cell lines with erlotinib, while showing robust cell death, enriches the ALDH+ cells through EGFR-dependent activation of the Notch pathway." (PMID 26474174, 2015). "For the first time, we demonstrate that NF-κB pathway activation may replace the oncogene signaling in lung cancer when effective and persistent inhibition of EGFR is achieved in the presence of the T790M mutation." (PMID 26015408, 2015). "Of several different testing methods available, PCR followed by directed sequencing and amplification refractory mutation system (ARMS) are the two most commonly used diagnostic methods worldwide to detect mutations at KRAS exon 2 and EGFR kinase domain exons 18-21 in lung cancer." (PMID 27127615, 2015). "Finally, we immunohistologically analyzed β-catenin localization in lung cancer tissues harboring EGFR TKI-sensitive mutations that were derived from patients who were subsequently treated with gefitinib." (PMID 26268703, 2015). "We suggest that EGFR mutation be verified for patients with lung cancer metastasized to the spine." (PMID 25452785, 2015). "Interestingly, PTEN loss conferred resistance against EGFR inhibitors in colorectal and lung cancer, against herceptin in breast cancer or even BRAF inhibitors in melanoma." (PMID 25646931, 2015). "Moreover, elevated levels of p-EGFR/Y1173 in primary lung cancer are associated with a poorer clinical response to anti-EGFR therapies." (PMID 26079946, 2015). "This principle is supported by the seminal finding that sensitizing epidermal growth factor receptor (EGFR) mutations are present in about 17 % of lung cancers and are targetable with the FDA approved EGFR tyrosine kinase inhibitors (TKIs) (erlotinib, gefitinib and afatinib)." (PMID 26668062, 2015). "In 2013, the College of American Pathologists, International Association for the Study of Lung Cancer, and Association for molecular Pathology established guidelines for the molecular testing of all advanced stage lung adenocarcinomas for EGFR mutations and ALK rearrangements prior to treatment." (PMID 26603430, 2015).
lung cancer (continued). "Thus, this study is the first to demonstrate that the EGFR-L858R mutant enhances the formation of MPE associated with lung cancer." (PMID 26338423, 2015). "However, de novo and acquired drug resistance mechanisms such as the gatekeeper T790M EGFR mutation have been observed in lung cancer patients." (PMID 25730908, 2015). "Our findings suggest a potential therapeutic impact of afatinib as a radiation sensitizer in lung cancer cells harboring acquired T790M mutation, providing a rationale for a clinical trial with combination of afatinib and radiation in NSCLCs with EGFR T790M mutation." (PMID 25714021, 2015). "EGFR mutated lung cancer accounts for a significant subgroup of non-small-cell lung cancer (NSCLC)." (PMID 26515464, 2015). "Therefore, the reliable detection of EGFR mutations is an important factor that allows the personalized treatment of lung cancer patients." (PMID 25719557, 2015). "We used a modified Boyden chamber assay to investigate whether the EGFR-L858R mutation affected the invasive behavior of lung cancer cells." (PMID 26338423, 2015). "Notably, when such activating PIK3CA mutations are introduced into EGFR-mutant lung cancer cells, they impart a partial resistance to TKIs." (PMID 25962919, 2015). "Notably, most lung cancer patients expressing the T790M EGFR mutation respond to initial gefitinib treatment but eventually acquire resistance." (PMID 26517520, 2015). "In some human lung cancers, genetic mutations are found in a genethat makes a protein called EGFR." (PMID 25686219, 2015). "The implications for future research are challenging: the EGFR mutated dosage as well as coexisting mutations could become a new predictive tool for lung cancer patients and new technologies, such as NGS, may potentially be introduced in routine practice." (PMID 25904052, 2015). "Inhibition of the EGFR pathway leads to the down-regulation of pro-survival signals and up-regulation of pro-apoptotic molecules, by which EGFR tyrosine kinase inhibitors (EGFR-TKIs) exert their dramatic effects in patients with EGFR mutated lung cancer." (PMID 26515464, 2015). "Finally, we have described a subset of lung carcinomas harboring EGFR and ALK mutations and overexpressing p16Ink4A that shows better clinical outcome compared to p16Ink4A-wild-type tumors." (PMID 26674347, 2015). "In addition, the identification of epidermal growth factor receptor (EGFR) mutations and the introduction of EGFR inhibitors to successfully treat EGFR mutated non–small cell lung cancers are breakthroughs for lung cancer treatment." (PMID 26091466, 2015). "In the pooled analysis from LUX-Lung 3 and 6, presented this year at ASCO, afatinib prolonged survival of lung cancer patients whose tumors have common EGFR mutations by a median of three months compared with standard chemotherapy and significantly reduced the risk of death by 19%." (PMID 25364578, 2014). "Driver mutations, including EGFR, have focused on lung cancer and other malignant tumors." (PMID 25490772, 2014). "Despite advances in the treatment of non-small cell lung cancers (NSCLC), for example, the development of EGFR tyrosine kinase inhibitors (EGFR TKIs) for patients with activating EGFR mutations, survival rates for patients with mutant-KRas lung cancer are poor." (PMID 25538889, 2014). "Previous studies have suggested potential mechanisms to explain the erlotinib activities in EGFR-wt lung cancers, such as EGFR copy numbers, mutations in other exons of the EGFR gene, cancerous inhibitor of protein phosphatase 2A (CIP2A) pathway and VeriStrat status." (PMID 25215536, 2014). "The second aim of this study is to confirm whether VOC patterns are able to detect histologically confirmed lung cancers, and driver mutations such as EGFR mutation." (PMID 25490772, 2014). "Furthermore, the epidermal growth factor receptor (EGFR) gene mutation is a predictor of gefitinib sensitivity in lung cancer." (PMID 25013503, 2014).
lung cancer (continued). "In line with this, we found that downregulation or inhibition of CK2α could lead to induction of autophagy in lung cancer cells with EGFR mutation." (PMID 25486409, 2014). "The analysis of VOC patterns including a decision tree algorithm may be useful to detect EGFR mutation emitted from lung cancer cell lines in the future." (PMID 25490772, 2014). "L858R is a recurrent lung cancer mutation which activates EGFR and also impacts drug binding." (PMID 24743239, 2014). "The specific mechanisms how lung cancer cells harboring epidermal growth factor receptor (EGFR) activating mutations can survive treatment with EGFR-tyrosine kinase inhibitors (TKIs) until they eventually acquire treatment-resistance genetic mutations are unclear." (PMID 25343452, 2014). "After screening twenty human lung cancer cell lines through expression patterns of E-cadherin and vimentin according to epithelial mesenchymal transition features, an H1975 cell line carrying EGFR mutations, L858R and T790M, was selected for investigation." (PMID 25462870, 2014). "In addition, upon scanning phosphorylation of EGFR across 31 lung cancer cell lines, they observed that higher stoichiometry of three phosphorylation sites was statistically correlated with EGFR sensitizing mutations." (PMID 28250368, 2014). "Our results showed that inhibition of DDX3X may be a promising therapy for overcoming primary EGFR-TKI-resistance mechanisms based on intratumor heterogeneity and for achieving a cure in lung cancer patients harboring EGFR-activating mutations." (PMID 25343452, 2014). "In addition to AXL overexpression, MET overexpression and the expression of its ligand, HGF have both been described as in vitro and in vivo mechanisms of resistance to EGFR TKI therapy in EGFR-mutated lung cancers." (PMID 25337673, 2014). "However, the frequency of patients with EGFR mutations in unselected lung cancer is 10-40%, depending on the ethnicity of the study population." (PMID 24658031, 2014). "EGFR mutations have now been clearly indicated as a marker of lung cancer." (PMID 24743427, 2014). "This may be attributed to the higher prevalence EGFR mutations in lung cancer patients from East than KRAS mutations." (PMID 24533074, 2014). "Our data suggested that DDX3X may represent a novel therapeutic target for overcoming intratumor heterogeneity in lung cancer patients harboring EGFR-activating mutations." (PMID 25343452, 2014). "A recent study from the perspective of the Chinese healthcare system investigated the cost-effectiveness of first-line erlotinib compared with platinum-doublet chemotherapy in advanced EGFR mutation positive lung cancer patients based on outcomes from the OPTIMAL trial." (PMID 25295228, 2014). "EGFR variant 3, NM_201283 is reported to be strongly associated to lung cancer by several studies." (PMID 25034693, 2014). "This was a rare case of a lung cancer that expressed amylase and harbored a positive EGFR mutation." (PMID 29147375, 2014). "The purpose of this study was to clarify whether TTF-1 expression status can be used to predict EGFR mutation status to guide clinical treatment and improve the prognosis of patients with advanced lung cancer." (PMID 24743427, 2014). "Our previous experience in lung cancer demonstrated that epidermal growth factor receptor (EGFR) mutations in serum could be a good predictive marker for lung cancer patients receiving EGFR tyrosine kinase inhibitors." (PMID 25496700, 2014). "Moreover, in EGFR mutant or KRAS mutant lung cancer models, tumor regression associated with apoptosis was observed only when the PI3K/AKT pathway and MEK/MAPK pathway were simultaneously blocked." (PMID 24337632, 2014). "Epidermal growth factor receptor (EGFR) has been found to correlate with key characteristics of cancer, including cell proliferation, apoptosis and tumor metastasis, and the dysregulation of EGFR has been associated with chemoresistance in lung cancer." (PMID 25009665, 2014).
lung cancer (continued). "We next investigated whether the differential effects of gefitinib between these lung cancer cell lines were associated with activation status of the EGFR signaling pathway." (PMID 24658031, 2014). "In addition, erlotinib and gefitinib, small-molecule EGFR inhibitors, are only indicated in EGFR mutation-positive lung cancer, most cases of which are ADCs." (PMID 25548429, 2014). "In addition, the majority of studies on the relationship between EGFR mutations and gefitinib have been performed in lung cancers; few studies have been published on data from NPC patients." (PMID 24602316, 2014). "This retrospective series reports multiple EGFR testing in lung cancer in routine diagnostic conditions and validates that molecular testing from single tumor-biopsy sample before first line EGFR-TKI may be conducted on any specimens." (PMID 24885034, 2014). "For example, combining AKT inhibition with EGFR TKI may improve response in lung cancer patients harboring EGFR mutations." (PMID 25763322, 2014). "Epidermal growth factor receptor (EGFR) is often hyper-activated in many lung cancers due to the presence of a mutation in the kinase domain, causing the activation of multiple cell survival signals, especially Akt and mitogen-activated protein kinase (MAPK) pathways." (PMID 25321484, 2014). "Besides xenograft experiments, one in vivo approach to test EGFR mutations consists in using transgenic mice in which lung cancer development is driven by inducible expression of the mutant protein." (PMID 24643470, 2014). "The early detection of EGFR-TKI resistance mutations may be beneficial in making treatment decisions for lung carcinoma patients, including those with SCLC." (PMID 24396447, 2014). "In the future, analyses of EGFR mutations in lung carcinoma, including SCLC, should be continued." (PMID 24396447, 2014). "The early detection of EGFR-TKI resistance mutations may be beneficial in making treatment decisions for lung carcinoma patients." (PMID 24396447, 2014). "Recent clinical studies have demonstrated that MET amplification predicts that patients with lung cancer and activating EGFR mutations will fail to respond to erlotinib or gefitinib, and KRAS mutation predicts that patients with colon cancer will fail to respond to cetuximab." (PMID 23577104, 2013). "Taken together, these results suggest that crizotinib plus either afatinib or WZ4002 may overcome the resistance to reversible EGFR-TKIs of EGFR mutant lung cancer cells containing an EGFR gatekeeper mutation, Met gene amplification, and/or HGF overexpression." (PMID 24386407, 2013). "Therefore, it is necessary to understand the correlations between EML4-ALK and EGFR/KRAS mutations in lung cancer patients." (PMID 23341890, 2013). "Therefore, the majority of clinical studies have demonstrated that the pleural metastasis of lung cancer was closely associated with the overexpression of EGFR, although certain others have reported contrary results." (PMID 24137392, 2013). "Complex EGFR mutations were reported to be more common in Asian lung cancer patients." (PMID 23590575, 2013). "However, recent advances with targeted therapies, such as epidermal growth factor receptor (EGFR)-tyrosine kinase inhibitors (TKIs), have resulted in marked benefit to subsets of lung cancer patients whose tumors have specific genetic mutations." (PMID 24369725, 2013). "Our results suggest that making use of immunoregulatory property of gefitinib may be a potential new therapeutical option for lung cancer with EGFR L858 + T790M resistance mutation." (PMID 23937717, 2013). "In addition, amplification of EGFR has been correlated with resistance in EGFR mutant lung cancer, although in the majority of cases the amplified allele harbors the T790M mutation." (PMID 24349229, 2013).